VWF (von Willebrand factor)
Diseases named in the same sentence as VWF in open-access papers (continued):
Sharing a sentence is not in itself a finding about the gene and the disease.
thrombosis (258 papers, 2007 to 2026). "TS is also associated with venous thrombosis and an increased number of circulating prothrombotic agents, such as von Willebrand factor or factor VIII." (PMID 40507741, 2025). "In contrast to the association observed between vWF: Ag levels and thrombosis, an association between AVWS and bleeding in patients with MPN has been previously reported." (PMID 41085687, 2025). "MTHFR 677-related mechanisms increase the risk of venous and arterial thrombosis, including endothelial toxicity, platelet activation, oxidation of low-density lipoproteins, and increases in von Willebrand factor and factor VII." (PMID 40276425, 2025). "A recent study demonstrated an association between high levels of vWF: Ag and splanchnic vein thrombosis specifically in patients with JAK2V617F-positive MPNs." (PMID 41085687, 2025). "Our findings add to these observations by confirming an association of elevated vWF levels to arterial as well as venous thrombosis and by demonstrating their predictive value." (PMID 41085687, 2025). "In the absence or reduction of ADAMTS13 activity, ultra-large von Willebrand factor strings remain anchored at the endothelium and can recruit flowing platelets and causing uncontrolled thrombosis in terminal arterioles and capillaries." (PMID 41160661, 2025). "Age, cardiovascular comorbidities and constitutional symptoms were significantly associated with thrombosis, as well as elevated von Willebrand Factor (vWF): Antigen, vWF: Activity and factor VIII levels." (PMID 41085687, 2025). "We did not observe an association between WBC counts, CRP, ferritin, D-dimer or fibrinogen levels and thrombosis; however, a strong association was observed between elevated levels of vWF: Ag, vWF: Ac and FVIII and TEs (p < 0.001 for all)." (PMID 41085687, 2025). "Despite this, there is a positive association of plasma VWF with the incidence of venous thrombosis, which is even stronger when considering unprovoked DVT." (PMID 39908367, 2025). "Deficiency results in the accumulation of ultra-large vWF that induces platelet aggregation and microvascular thrombosis." (PMID 40013218, 2025). "The strong association observed between vWF: Ag levels and both arterial and venous thrombosis in patients with MPN is a novel finding." (PMID 41085687, 2025). "Coagulation-related genes such as von Willebrand factor (vWF) and Tissue Factor are crucial for NETs-associated thrombosis." (PMID 40290435, 2025). "Different from the previous study, serum vWF levels in the present study reflect endothelial cell status and thrombosis risk." (PMID 40135640, 2025). "VWF and NETs play key roles in the formation of thrombi in the venous and arterial systems as well as the formation of cancer-associated thrombosis." (PMID 38965511, 2024). "Recent studies have shown that higher concentrations of the majority of procoagulant factors (FII, FVII, FVIII, FIX, FX, FXI, fibrinogen, and VWF) are associated with an increased risk of venous thrombosis." (PMID 38169400, 2024). "Pro-coagulant vWF promotes platelet adhesion and smooth muscle cell proliferation, and elevated levels of vWF have been associated with higher risk for thrombosis and cardiovascular disease." (PMID 38374351, 2024). "Factor VIII and its carrier protein VWF are associated with the risk of arterial and venous thrombosis." (PMID 39199353, 2024). "High circulating levels of unfolded VWF are known to be associated with thrombosis, e.g. in TTP, sickle cell disease, and myocardial infarction." (PMID 39726607, 2024). "This is consistent with the results of a previous study that showed that high FVIII and vWF levels were significantly associated with an increased risk of death in patients with venous thrombosis and also in individuals from the general population." (PMID 39175055, 2024). "Of these, increased levels of factor VIII:C and the von Willebrand factor were found to be most strongly associated to higher risks of venous thrombosis." (PMID 39487855, 2024).
thrombosis (continued). "In this study, whole exome sequencing (WES) was performed on a large Italian family with high/extremely high levels of FVIII and VWF and episodes of thrombosis to identify new genetic risk factors associated with FVIII/VWF increase." (PMID 37762470, 2023). "By using the TLR2-dependent activation of the NF-κB pathway in a MyD88-dependent manner, SARS-CoV-2 S protein induces inflammation and promotes vWF transcription, causing in situ thrombosis, as vWF binds to platelets, neutrophils, and monocytes." (PMID 36979908, 2023). "In patients with a history of coronavirus infection, the secretion of vWF increases, which leads to thrombosis and can be a cause of death." (PMID 38132876, 2023). "When endothelial cells are damaged, vWF expression increases, and this increase is associated with atherosclerosis and thrombosis." (PMID 37909014, 2023). "An increased level of vWF in obese patients is associated with thrombosis and cardiovascular disease." (PMID 38203423, 2023). "It is worth noting that VWF Arg1399His has been found to be strongly associated with deep-vein thrombosis (OR 3.26, 95% CI 1.18–8.98), at variance with most of the VWF missense changes, which predict bleeding conditions." (PMID 37762110, 2023). "A positive correlation was identified between ELAM-1 and ICAM-1 and VWF and between VWF and the allele burden and thrombosis." (PMID 35626232, 2022). "We also observed VWF associated with shortened thrombosis-free survival in AECA-positive PV patients." (PMID 35626232, 2022). "Variations in VWF levels are clinically significant because high levels of VWF are associated with thrombosis." (PMID 36080270, 2022). "The patients that developed thrombosis had elevated levels of established risk factors for thrombosis such as higher VWF and FVIII levels and lower ADAMTS-13 levels." (PMID 35482749, 2022). "Intense deficiency of ADAMTS-13 results in accumulation of ultra-large VWF multimers and causes microvascular thrombosis, thrombocytopenia and thrombotic thrombocytopenic purpura (TTP)." (PMID 36128671, 2022). "ADAMTS-13 deficiency results in vWF multimers built up and subsequent microvascular thrombosis and thrombocytopenia, a condition also known as thrombotic thrombocytopenic purpura (TTP)." (PMID 36295093, 2022). "Although RVO is caused by venous thrombosis, few clinical studies have examined the association between VWF and RVO; and these studies have reported different results." (PMID 36137144, 2022). "So that, inflammatory cytokines (IL-8 and TNF- α) cause the secretion of VWF from human endothelial cells and then VWF binds to NETs to induce thrombosis." (PMID 36128671, 2022). "Increases in plasma vWF induced by a single nucleotide polymorphism (rs1063856) in exon eight of vWF are associated with a higher risk of venous thrombosis." (PMID 35250627, 2022). "Various infectious diseases including HIV, malaria, scrub typhus, and Dengue virus infection have been associated with thrombosis and increased circulating VWF levels." (PMID 34575297, 2021). "There are several reviews discussing the role of vWF in platelet activation and inflammation bringing vWF fame of a risk factor for both arterial and venous thrombosis." (PMID 34235190, 2021). "Von Willebrand factor (vWF) is synthesized in endothelial cells, and increased plasma levels of vWF are in correlation with thrombosis risk and reversely with bleeding risk." (PMID 33799869, 2021). "In people with poor LA function and LA remodelling, vWF has been implicated in the development of LA thrombosis." (PMID 33925795, 2021). "In maintenance hemodialyzed patients, the KYN/TRP ratio is positively associated with thrombosis markers such as thrombomodulin and von Willebrand factor." (PMID 33803899, 2021). "Previous studies have also confirmed the pathogenic role of vWF in both arterial and venous thrombosis." (PMID 33925795, 2021).
thrombosis (continued). "In contrast to VWF deficiency, increased plasma VWF levels and functional activity is a significant risk factor for thrombosis." (PMID 34575297, 2021). "Tissue factor (TF) was identified as a direct target of miR-145, whereas miR-885 was found to activate the von Willebrand factor (vWF); miR-424 has been associated with hypercoagulability, whereas low levels of miR-103a are linked to deep-vein thrombosis." (PMID 35062245, 2021). "Increasing studies indicate that NETs, like VWF, play an important role in the formation of thrombus in venous, arterial, and cancer-associated thrombosis." (PMID 33343584, 2020). "Increased active VWF can potentially have major impact on the risk of bleeding and/or thrombosis, as exemplified by VWD type 2B and TTP." (PMID 30759116, 2019). "In our patient cohort, VWF and the ADAMTS‐13/VWF were associated with occurrence of cancer‐associated thrombosis." (PMID 31294335, 2019). "Studies have proven that an elevated circulating level of vWF is a risk factor for arterial and venous thrombosis." (PMID 26885523, 2016). "This is supported by studies showing that higher levels of plasma VWF due to a single nucleotide polymorphism (rs1063856) in exon eight of VWF are associated with an increase in venous thrombosis risk." (PMID 25297919, 2015). "VWF:FVIII concentrates should be used with caution in patients who have known risk factors for thrombosis; they are rarely linked with venous thromboembolism (VTE) associated with high levels of FVIII." (PMID 25960895, 2015). "A combination of derived EGLN1 allele (HAPE associated) and ancestral VWF allele (thrombosis associated) was significantly high in Kapha group compared to Pitta (p < 10–5)." (PMID 26047609, 2015). "Both Pitta and high altitude natives had the genotype in EGLN1 that was HA associated and VWF that was linked to protection from thrombosis." (PMID 26047609, 2015). "The ancestral ‘C’ allele of VWF rs1063856 has been associated with elevated plasma von Willebrand factor levels and the risk of incident venous thrombosis." (PMID 26047609, 2015). "It is plausible that ABO modulation of VWF-related thrombosis accounts for the ABO association with MI." (PMID 23133757, 2012). "Elevated levels of factor VIII (FVIII) and von Willebrand Factor (vWF) are well-established risk factors for cardiovascular diseases, in particular venous thrombosis." (PMID 21810271, 2011). "The AB alleles of the ABO blood group, high FVIII levels and von Willebrand factor (vWF) have been associated to a risk of venous thrombosis." (PMID 21637678, 2009). "Elevated VWF levels are frequently found in patients with cerebral sinus and venous thrombosis (CSVT), always in association with high F VIII levels." (PMID 24179341, 2008). "The JAK-2 V617F-mutation, a transversion mutation at nucleotide 1849 of JAK2, results in a valine-to-phenylalanine substitution at codon 617 and is associated with an increased risk of venous thrombosis via endothelial over-expression of the von Willebrand factor and p-selectin." (PMID 40792243, 2025). "High VWF was also found to be associated with thrombosis risk." (PMID 40217494, 2025). "A pathogenic role of VWF in venous thrombosis presents certain conceptual issues." (PMID 39908367, 2025). "Furthermore, patients with HHT often exhibit elevated levels of factor VIII and von Willebrand factor, which directly correlate with an increased risk of thrombosis." (PMID 40248535, 2025). "Consequently, disrupted endothelial integrity contributes to platelet activation, leukocyte recruitment, and dysregulated release of von Willebrand factor (vWF), predisposing to microvascular thrombosis and macrovascular events." (PMID 38996158, 2024). "Von Willebrand factor (vWF) is upregulated in MDA5+ DM causing thrombosis and ischemia." (PMID 39886283, 2024). "Thus, therapeutic strategies targeting PF4 and VWF-associated thrombosis are novel methods for the diagnosis and treatment of immune-associated thrombosis." (PMID 36926331, 2023).
thrombosis (continued). "Polymorphisms of vWF might modulate the function of the protein, and these genetic variations were suggested to contribute to the risk of venous thrombosis." (PMID 36980889, 2023). "Additionally, a high concentration of VWF independently increases the risk of deep vein thrombosis formation." (PMID 38075262, 2023). "Venous thrombosis in large veins is initiated with the local inflammation of venous endothelial cells, which causes locally increased expression of surface selectins and VWF." (PMID 36361963, 2022). "Individuals with renal insufficiency with increased VWF levels may have an increased risk of venous thrombosis." (PMID 36209090, 2022). "To date, vWF has been linked to both, arterial and venous thrombosis." (PMID 35054824, 2022). "Severe deficiency plasma ADAMTS13 activity may lead to increased size of VWF multimers and increased risk of microvascular thrombosis such as thrombotic thrombocytopenic purpura." (PMID 36362664, 2022). "Pro-inflammatory factors such as von Willebrand factor and fibrinogen are intended to prevent excessive blood loss after birth, but in certain women, this effect is exaggerated causing them to have an elevated risk of thrombosis." (PMID 36233801, 2022). "Although several studies have proposed an association between venous thrombosis and von Willebrand factor (VWF), the association between RVO and VWF remains unclear." (PMID 36137144, 2022). "Raised FVIII/VWF levels of >150% are known to be significant risk factors for thrombosis." (PMID 33806540, 2021). "Furthermore, the incidence of arterial thrombosis is significantly reduced in patients with VWD and there is increasingly more evidence that inflammation can cause VWF-mediated thrombosis." (PMID 33919627, 2021). "VWF is also known as a risk factor for macrovascular thrombosis." (PMID 33806540, 2021). "Mice deficient in vWF were protected from induced deep vein thrombosis." (PMID 33925795, 2021). "These may explain the higher incidence of thrombosis in older individuals, since Fbg, FVIII and VWF are the three acknowledged risk factors for thrombosis." (PMID 28382235, 2017). "However, it is of great interest to discover new determinants of the excretion mechanism of VWF molecules, since high VWF levels have been associated with venous thrombosis and arterial thrombosis." (PMID 24626470, 2014). "The ability to selectively and quickly release small inflammatory chemokines prior to bulk WPB cargo may provide a mechanism to control inflammatory processes, while retention and delay of VWF/Pro-VWF release reduces a risk of associated thrombosis." (PMID 25233365, 2014). "Although it has been well documented since the 1960s that Fg is required for platelet aggregation, using an FeCl3 injury intravital microscopy thrombosis model, we demonstrated that occlusive thrombus formation still occurred in both Fg−/− and Fg/VWF double deficient (Fg/VWF−/−) mice." (PMID 23008717, 2012). "Moreover, VWF level in humans also correlates directly with thrombosis risk and inversely with bleeding risk." (PMID 22091368, 2010). "Moreover, exploring the role of the vWF and other coagulation factors in cancer-associated thrombosis and autoimmune diseases may reveal important mechanistic insights relevant to CAD pathophysiology." (PMID 41007843, 2025). "Thus, the association of ABO and vWF with cardiovascular disease is mainly seen among those with an atherosclerotic event, including thrombosis, such as MI or ischemic stroke, whereas other factors influence the early and ongoing progression of atherosclerosis." (PMID 39844181, 2025). "Additionally, vWF/FBLN5 upregulation may be a novel mechanism for virus-associated thrombosis/coagulation." (PMID 38649864, 2024). "The level of VWF in the high-risk group of thrombosis after orthopedic surgery was significantly higher than that in the low-risk group of preoperative thrombosis, suggesting that VWF may be used as a potential thrombus biomarker in orthopedic surgery patients." (PMID 36944974, 2023).
thrombosis (continued). "High VWF and decreased plasma fibrinolytic potential, however, are established risk factors for venous and arterial thrombosis, and we therefore speculate that the unbalanced hemostasis in patients one year after OLT may contribute to their increased risk for thrombotic events." (PMID 25285204, 2014). "Research shows a strong correlation between thrombosis, stroke prognosis, and inflammatory markers such as von Willebrand factor (VWF), CD147, CD163, C-reactive protein (CRP), neutrophil extracellular trap (NET), and Actin." (PMID 41036279, 2025). "ADAMTS13-resistant von Willebrand factor–platelet tangles are the nidus for venous thrombosis development." (PMID 39908367, 2025). "Plasminogen Activator Inhibitor-1, von Willebrand Factor, and D-dimer show thrombosis whereas NT-proBNP reflects cardiac stress." (PMID 39854741, 2025). "Elevated vWF: Antigen levels remained independent in multivariate analysis and were predictive of incident thrombosis." (PMID 41085687, 2025). "We found that TF, FVIII, and FIX are related to cancer cell-derived MV-induced thrombosis, whereas VWF plays a very limited role in this process." (PMID 40217494, 2025). "Part of this association can be attributed to the association of VWF levels with those of plasma factor VIII, which is a positive modifier of venous thrombosis risk." (PMID 39908367, 2025). "In a study of human patients with atrial fibrillation, vWF quantity and function are directly proportional to LA function and are independent predictors of intracardiac thrombosis." (PMID 40509097, 2025). "Not only ADAMTS-13 variants but also VWF and FVIII variants can be responsible for plasma levels of these molecules and thrombosis risk." (PMID 40557182, 2025). "Under oscillatory flow patterns in the presence of ADAMTS13, the VWF-platelet tangles and knots that formed on the endothelial surface bear resemblance to the pattern of platelet accumulation during the initiation of venous thrombosis in the stenosis model." (PMID 39908367, 2025). "TTP, typically characterized by a deficit in the activity (< 10%) of ADAMTS13 leading to the accumulation of ultra‐large VWF multimers platelet aggregation, endothelial damage, and microvascular thrombosis and ischemia, shows an incidence of < 1/100 000/year." (PMID 40206570, 2025). "This has led to the contention that VWF function is more important at arterial than venous shear stress, although numerous studies support a role for VWF in the pathogenesis of venous thrombosis." (PMID 39908367, 2025). "Thrombosis occurs when platelets adhere to the complex formed by collagen and von Willebrand factor (vWF)." (PMID 41246026, 2025). "The cytokine-mediated suppression of ADAMTS13 activity results in VWF imbalances, which lead to microvascular thrombosis and unfavorable clinical outcomes, particularly in patients with disseminated intravascular coagulation." (PMID 40725629, 2025). "Despite this, the platelet-binding function of VWF appears to be of primary importance in venous thrombosis initiation." (PMID 39908367, 2025). "Histological classification of the identified clots or clot-free areas seems to be a promising way to identify mechanism of clot formation including flow-induced thrombosis (vWF)." (PMID 38962744, 2024). "Mendelian randomization suggested the causal effects of plasma FVIII activity levels on venous thrombosis and CAD risk, and of plasma VWF levels on ischemic stroke risk." (PMID 39199353, 2024). "In conclusion, we found a significant association between unfolded VWF levels above the 90th percentile cut-off value and the occurrence of APS and thrombosis in general." (PMID 39726607, 2024). "The ADAMTS13/VWF ratio is considered a sensitive index to evaluate blood flow in liver-related splanchnic vein thrombosis." (PMID 38672756, 2024).